PIAS3 (protein inhibitor of activated STAT 3)
Diseases named in the same sentence as PIAS3 in open-access papers (continued):
Sharing a sentence is not in itself a finding about the gene and the disease.
colon cancer (4 papers, 2014 to 2024). "A previous study reported that miR-181b is a direct regulator of PIAS3 that activates the STAT3 signaling pathway in colon cancer." (PMID 34980138, 2022). "In the present study, we found PIAS3 overexpression decreased the r glucose consumption and lactic acid production in vitro, and inhibited the growth of colon cancer xenografts in vivo." (PMID 30054984, 2018). "miR‐181b expression interacted with STAT3 phosphorylation in a positive feedback loop in colon cancer cells via regulating PIAS3 expression." (PMID 30054984, 2018). "In conclusion, this study for the first time demonstrated that miR‐181b contributed to the Warburg effect and xenograft tumour growth of colon cancer by targeting PIAS3." (PMID 30054984, 2018). "In the present study, we validated that miR‐181b activated STAT3 in colon cancer cells, and furthermore PIAS3 mediated the effect of miR‐181b on STAT3 activation." (PMID 30054984, 2018). "This study suggested that miR-181b/PIAS3/STAT3 axis may be a key target for colon cancer therapy regarding its effect on cell growth and metabolism." (PMID 38185635, 2024). "This study suggested miR‐181b/PIAS3/STAT3 axis as a novel target for colon cancer treatment." (PMID 30054984, 2018). "To investigate whether PIAS3 mediated the effect of miR‐181b on aerobic glycolysis in colon cancer cells, we synthesized three PIAS3 siRs to knockdown PIAS3 and found that PIAS3 siR‐3 was the most efficient siRNA." (PMID 30054984, 2018). "In the present study, we explored the relationship between miR‐181b (miR‐181b‐5p), PIAS3 and STAT3, and investigated the function of miR‐181b/PIAS3/STAT3 axis on the Warburg effect and xenograft tumour growth of colon cancer." (PMID 30054984, 2018). "This study aimed to investigate the relationship between the expression of microRNA (miR)‐181b, protein inhibitor of activated STAT3 (PIAS3) and STAT3, and to examine the function of the miR‐181b/PIAS3/STAT3 axis on the Warburg effect and xenograft tumour growth of colon cancer." (PMID 30054984, 2018). "The gain‐of‐function and loss‐of‐function experiments were performed on HCT 116 cells to investigate the effect of miR‐181b/PIAS3/STAT3 on the Warburg effect and xenograft tumour growth of colon cancer, as determined by commercial kits and xenograft experiments." (PMID 30054984, 2018). "Also, previous research reported that miR-181b also serves as a direct regulator of PIAS3, and its overexpression could downregulate PIAS3, leading to STAT3 activation through phosphorylation in positive feedback in colon cancer cells." (PMID 38185635, 2024).
melanoma (4 papers, 2012 to 2024). A malignant, usually aggressive tumor composed of atypical, neoplastic melanocytes. "BL6-B16 melanoma cells were co-transfected with MITF and PIAS3." (PMID 22316093, 2012). "We find that the experimentally observed crosstalk between MITF and STAT3 via PIAS3 in melanocytes is faithfully reproduced in our model, offering mechanistic explanations for this behaviour, as well as providing a scaffold for further studies of MITF signalling in melanoma." (PMID 22316093, 2012).
multiple myeloma (4 papers, 2017 to 2021). "In addition to the induction of PTPs, 3FC has been described to repress STAT3 activity through the expression of PIAS3 in multiple myeloma cells." (PMID 35053027, 2021). "Exosomal miR-21 from NSCLC cells facilitates osteoclastogenesis by targeting PDCD4 and inhibition of miR-21 impairs osteoclast activity in multiple myeloma by targeting OPG and PIAS3." (PMID 33800656, 2021).
ovarian carcinoma (4 papers, 2011 to 2024). A malignant neoplasm originating from the surface ovarian epithelium. "We therefore attempted to illustrate these genomic and epigenetic sample irregularities (such as observed in PLAGL1, CCNE1 and PIAS3) for many of the known ovarian cancer genes." (PMID 22174824, 2011).
rheumatoid arthritis (4 papers, 2018 to 2022). A chronic, systemic autoimmune disorder characterized by inflammation in the synovial membranes and articular surfaces. "For instance, synovial MSC-derived exosomal circRNAs have therapeutic potential on rheumatoid arthritis (RA) via targeting circEDIL3/miR-485-3p/PIAS3/STAT3/VEGF function module." (PMID 36339941, 2022). "Furthermore, FOXD2-AS1 reinforces the progression of rheumatoid arthritis by regulating the miR-331-3p/PIAS3 pathway." (PMID 36551318, 2022). "Further, miR-301a-3p is highly expressed in peripheral blood mononuclear cells (PBMCs) from rheumatoid arthritis (RA) patients and attenuate expression of protein inhibitor of activated STAT3 (PIAS3) to regulate differentiation of Th17 cells." (PMID 29599779, 2018). "The expression of protein inhibitor of activated STAT3 (PIAS3) showed negative correlation with the level of Th17 in rheumatoid arthritis (RA) patients, and mice model of graft-versus-host disease revealed that PIAS3 upregulates Th17 population and downregulates Treg population." (PMID 30630513, 2019).
squamous cell lung carcinoma (4 papers, 2015 to 2024). A carcinoma arising from squamous bronchial epithelial cells. "PIAS3 protein levels are often downregulated, and low PIAS3 expression is associated with poor survival of squamous cell lung cancer patients." (PMID 34503213, 2021). "This necessitates the discovery of other small molecule activators of PIAS3 expression, perhaps a preexisting therapeutic agent, if we hope to achieve our goal of PIAS3-targeted therapy in squamous cell lung cancer." (PMID 25573684, 2015). "Another key area to explore is when in the process of squamous cell lung cancer development does PIAS3 expression decrease?" (PMID 25573684, 2015). "Taken together, these results reveal the importance of PIAS3 as a tumor suppressor of STAT3 activity in squamous cell lung cancer." (PMID 25573684, 2015). "The clinical significance of low PIAS3 expression was demonstrated in a large cohort of 133 squamous cell lung cancer patients registered in the TCGA database." (PMID 25573684, 2015). "We next used western blotting to confirm the low expression of PIAS3 protein in squamous cell lung cancer." (PMID 25573684, 2015). "To investigate further the distinct PIAS3 suppression in the majority of squamous cell lung cancer specimens and its potential clinical impact, we used the TCGA database to correlate PIAS3 mRNA transcript levels with overall survival in a cohort of 133 squamous cell lung cancer patients." (PMID 25573684, 2015).
cervical cancer (3 papers, 2014 to 2022). A primary or metastatic malignant neoplasm involving the cervix. "In cervical cancer samples, as well as in cell lines associated with cervical cancer, PIAS3 is downregulated, while the microRNA miR-199a-5p that plays an oncogenic role by promoting cell proliferation, EMT and metastasis, shows high levels of expression." (PMID 35887358, 2022). "Contrastingly, in cervical cancer, miR-199a-5p promotes the same aspects—proliferation, migration, and EMT—via direct targeting of protein inhibitors of activated signal transducer and activators of transcription 3 (PIAS3)." (PMID 34884646, 2021).
medulloblastoma (3 papers, 2011 to 2018). A malignant, invasive embryonal neoplasm arising from the cerebellum. "Further, protein inhibitor of activated STAT3 (PIAS3) has been found to be downregulated in medulloblastomas, and resveratrol shown to significantly upregulate PIAS3 in UW228-2, UW228-3, and DAOY cells with the repression of p-STAT3 levels." (PMID 29495357, 2018). "Alternatively, it would be more convincing if the levels of SHP2, SOCS1/SOCS3 and/or PIAS3 are altered accordingly in medulloblastoma cells with suppressed STAT3 signaling." (PMID 28035977, 2016). "In the future, we will further elucidate the influence of PIAS3 manipulation in the survival and resveratrol sensitivities of medulloblastoma cells." (PMID 28035977, 2016). "The results revealed the general reductions of p-SHP2, SOCS3 and especially PIAS3 levels in the three medulloblastoma subtypes with frequent p-STAT3 nuclear translocation." (PMID 28035977, 2016). "In resveratrol-suppressed medulloblastoma cells with STAT3 downregulation and decreased incidence of STAT3 nuclear translocation, PIAS3 is upregulated, the SHP2 level remains unchanged and SOCS3 is downregulated." (PMID 28035977, 2016). "It is found that upon resveratrol treatment, PIAS3 is up-regulated and translocalized in nuclei, SOCS3 level is reduced and SHP2 remains unchanged in the three medulloblastoma cells so far checked." (PMID 28035977, 2016). "Therefore, the resveratrol-treated medulloblastoma cells would be an ideal model to evaluate the role of SHP2, SOCS3 or PIAS3 in regulating STAT3 signaling." (PMID 28035977, 2016). "SHP2, SOCS3 and PIAS3 are known as the negative regulators of STAT3 signaling, while their relevance to frequent STAT3 activation in medulloblastomas remains unknown." (PMID 28035977, 2016). "PIAS3 upregulation and nuclear translocation in resveratrol-treated medulloblastoma cells with suppressed STAT3 signaling further suggests the negative regulatory effects of PIAS3 on STAT3 signaling and the potential value of PIAS3 in evaluating the prognosis of medulloblastoma patients." (PMID 28035977, 2016). "Inverse correlation could be established between p-SHP2 (R = −0.35; p = 0.029), SOCS3 (R = 0.495; p = 0.001) or PIAS3 expression (R = −0.352; p = 0.020) and p-STAT3 nuclear translocation in the classic medulloblastomas." (PMID 28035977, 2016).
Alzheimer disease (2 papers, 2021 to 2024). A progressive, neurodegenerative disease characterized by loss of function and death of nerve cells in several areas of the brain leading to loss of cognitive function such as memory and language. "It has also been reported that PIAS3 reduces the activated form of STAT3, increases the activity of the downstream Nestin/Nrf2/HO‐1 pathway, and inhibits damage in Alzheimer's disease model SH‐SY5Y cells." (PMID 39496070, 2024).
Arthritis (2 papers, 2019 to 2021). Inflammation of a joint. "The arthritis score (histologic score of peripheral joints) of PIAS3-treated mice was significantly lower than that of Mock-treated mice, and a gross histology image revealed that the joint structure of PIAS3-treated mice was more preserved than that of Mock-treated mice." (PMID 30630513, 2019).
endometrial cancer (2 papers, 2015 to 2020). Primary or metastatic malignant neoplasm involving the endometrium (mucous membrane that lines the endometrial cavity). "ovarian and endometrial cancers: curcumin suppresses JAK-STAT signaling via activation of PIAS-3, thus attenuating STAT-3 phosphorylation and tumor cell growth." (PMID 32927725, 2020). "Indeed, Calu-1 cells, a model of SCC PIAS3 deficiency, also responded to curcumin treatment with concentration-dependent PIAS3 overexpression, confirming a previous observation in ovarian and endometrial cancer cells." (PMID 25573684, 2015).
endometriosis (2 papers, 2019 to 2022). The growth of functional endometrial tissue in anatomic sites outside the uterine body. "In support of PIAS3 having an active role in preventing endometriosis, an in vitro study has shown that INFγ can reduce PIAS3 but increases p-STAT3, suggesting aberrant STAT3 activation by attenuation of PIAS3." (PMID 35203298, 2022). "One potential mechanism suggested for increased STAT3 activation in endometriosis is down-regulation of protein inhibitor of activated STAT3 (PIAS3) which has been observed in women and non-human primates with endometriosis." (PMID 31387263, 2019).
HCMV infection (2 papers, 2021 to 2024). "Furthermore, the physiological association of UL44 with PIAS3 during HCMV infection was also directly demonstrated in HCMV-infected U251 cells with native antibodies (non-tagged)." (PMID 34747321, 2021). "We thus constructed the U251-PIAS3 host cells capable of stably overexpressing PIAS3 for wt-HCMV infection." (PMID 34747321, 2021). "Therefore, PIAS3 was screened out to be a novel SUMO-related protein capable of direct interaction with UL44 during HCMV infection of human cells." (PMID 34747321, 2021). "In addition, HCMV infection assays also hinted the physiological correlation of UL44 SCM site with PIAS3." (PMID 34747321, 2021). "WT HCMV infection also substantially increased the accumulation of PIAS-type E3-SUMO ligases, including PIAS1, PIAS3, and PIAS4, as well as PIAS2, albeit to a much lesser extent." (PMID 38768227, 2024). "Moreover, immunofluorescence localization analyses on the wt-HCMV infection showed that upon interference of endogenous PML by siPML, the UL44-wt distribution, as well as that of PIAS3, turned from the nuclear foci to nuclear extensive diffusion (ix versus x)." (PMID 34747321, 2021). "Considering the PIAS3 role in inhibition of activated STAT3 pathway and the identified PIAS3 interaction with UL44, there might be a possibility that the STAT3 activity could be enhanced by competitive UL44 binding to PIAS3 during HCMV infection." (PMID 34747321, 2021). "Collectively, after HCMV infection, SCM-specific SUMOylation confers UL44 protein co-localization with the PML component of ND10 compartments, which is not the indirect recruitment by PIAS3." (PMID 34747321, 2021).
hepatocellular carcinoma (2 papers, 2014 to 2024). A malignant tumor that arises from hepatocytes. "The study identifies PIAS3 as a key promoter of ferroptosis in hepatocellular carcinoma (HCC) by regulating TXNIP through TGF-β signaling, suggesting a novel therapeutic target for enhancing ferroptotic sensitivity in HCC treatment." (PMID 39315094, 2024). "The SUMO E3 protein PIAS3 is upregulated in several different cancer types, and elevated levels of the SUMO E1 enzyme are associated with more severe hepatocellular carcinomas." (PMID 24971752, 2014).
ischemia (2 papers, 2022 to 2024). A hypoperfusion of the BLOOD through an organ or tissue caused by a PATHOLOGIC CONSTRICTION or obstruction of its BLOOD VESSELS, or an absence of BLOOD CIRCULATION. "Next, we evaluated the neuroprotective effect of the PINIT domain of PIAS3 against transient global ischemia-induced neuronal injury." (PMID 38456949, 2024). "Disruption of the MLK3-PIAS3 interaction by the PINIT domain of PIAS3 inhibited MLK3 SUMOylation and its downstream apoptotic signaling and reduced neurological deficits in neuronal and rodent ischemia models." (PMID 38456949, 2024). "The recombinant AAV encoding the PINIT domain of PIAS3 (AAV-PINIT) and negative control empty vector AAV (AAV-NC) were injected into the bilateral rat hippocampal CA1 region, an area vulnerable to global ischemia, with two points in each hemisphere." (PMID 38456949, 2024). "We speculated that during ischemia, increased BDNF expression could reduce synaptic abundance of GABAARs via PIAS-3–mediated gephyrin modification at K148 and K724 residues." (PMID 35307349, 2022).
non-small cell lung carcinoma (2 papers, 2014 to 2019). A group of at least three distinct histological types of lung cancer, including non-small cell squamous cell carcinoma, adenocarcinoma, and large cell carcinoma. "It was also observed that PAI-1/PIAS3/Stat3/miR-34a feedback loop enhanced EMT-mediated metastasis through Stat3 signaling in non-small cell lung cancer (NSCLC)." (PMID 31170987, 2019). "The prespecified hypothesis tested was that STAT5, COX-2 and PIAS3 expression levels were modified in non-small cell lung cancer, playing a role in lung carcinogenesis." (PMID 25137041, 2014).
squamous carcinoma (2 papers, 2014 to 2015). "Importantly, four of five squamous carcinoma cell lines demonstrated equivalent to lower PIAS3 expression level compared to NL20 cells, and further decreased compared to the level in A549 cells." (PMID 25573684, 2015). "The expression rates of intrinsic STAT3 inhibitor PIAS3 were 52.6% (20/38) among noncancerous epithelial tissues but reduced to 16.0% (4/25; p<0.01) and 11.6% (5/43; p<0.01) in cervical adenocarcinoma and squamous carcinoma samples, respectively." (PMID 25061499, 2014).
breast tumor (1 paper, 2024). "PIAS3 reduction in breast tumor promotes the PIAS3 and Smurf2 pathway in tumor progression and metastasis; PIAS3-Smurf2 SUMOylation mechanism still requires more investigation in breast tumor metastasis." (PMID 38590645, 2024).
Cerebral ischemia (1 paper, 2024). Restriction of arterial blood supply to the brain associated with insufficient oxygenation to support the metabolic requirements of the tissue. "PIAS3 regulates the transcription activity of signal transducer and activator of transcription 3 (STAT3), which has been implicated in cerebral ischemia." (PMID 38456949, 2024). "In the study, we identified an additional mechanism for MLK3 regulation by SUMOylation, and PIAS3 facilitated MLK3 SUMOylation after cerebral ischemia." (PMID 38456949, 2024). "Our findings demonstrate that brain ischemia-induced MLK3 SUMOylation by PIAS3 is a potential target against poststroke neuronal lesions and behavioral impairments." (PMID 38456949, 2024). "SUMOylation of MLK3 dramatically increased in the presence of PIAS3.These data suggest that PIAS3 facilitates MLK3 SUMOylation following brain ischemia." (PMID 38456949, 2024). "Our results reveal that cerebral ischemia induces MLK3 SUMOylation in the hippocampus and cortex by promoting the interaction of the SUMO ligase PIAS3 and that AAs 133–320 in PIAS3 directly bind MLK3." (PMID 38456949, 2024).
chronic hepatitis C virus infection (1 paper, 2017). Chronic form of hepatitis C infection. "In a similar correlation of PIAS3 levels and viral pathogenesis, increased PIAS3 levels are also associated with relapse of chronic hepatitis C virus infection and resistance to interferon-α treatment; however, the mechanism for the events remain to be clarified." (PMID 28705221, 2017).
Cirrhosis (1 paper, 2015). A chronic disorder of the liver in which liver tissue becomes scarred and is partially replaced by regenerative nodules and fibrotic tissue resulting in loss of liver function. "Although differential gene expression in HCV cirrhosis has revealed a proapoptotic gene profile, a positive antiapoptotic balance through impaired Stat3 DNA-binding and Pias3 (protein inhibitor of activated Stat) upregulation has been documented in end-stage cirrhosis." (PMID 25892989, 2015). "Although Stat3 expression and phosphorylation was not altered in HCV-mediated cirrhosis, a significantly weak Stat3 DNA-binding activity was observed in nuclear extracts from human cirrhotic liver samples with an associated upregulation of Pias3 expression." (PMID 25892989, 2015).
demyelination (1 paper, 2021). "Interestingly, in this study, only miR-301a was found to be involved in Th17 differentiation and the pathogenesis of demyelination via Protein Inhibitor of Activated STAT 3 (PIAS3) molecule (affecting IL-6/23–STAT3 pathway) as a direct target in CD4+ T-cells." (PMID 33919306, 2021).
infarction (1 paper, 2022). A localised pathological necrosis of tissue resulting from obstruction of the blood supply usually by a thrombus, an embolus, or vascular torsion. "Lastly, miR-18a-5p appears to have a causal effect on PIAS3, which was involved in infarction and inflammation." (PMID 36140236, 2022).
large cell medulloblastoma (1 paper, 2016). A medulloblastoma composed of large cells with prominent nucleoli and a larger amount of cytoplasm in contrast with the cells of the classic medulloblastoma. "Statistical correlations were established between p-STAT3 nuclear translocation and the level of SOCS3 (R = 0.333; p = 0.047) or PIAS3 expression (R = −0.494; p = 0.002) but not p-SHP2 down-regulation (R = 0.02; p > 0.05) in the large-cell medulloblastomas." (PMID 28035977, 2016).
liver cirrhosis (1 paper, 2022). "Another study reported that in liver cirrhosis, STAT3 DNA-binding is impaired by raising the expression of Pias3." (PMID 36297027, 2022).